MIR1251 (microRNA 1251)
Synonyms: hsa-mir-1251; MIRN1251
Gene: MicroRNA gene on chromosome 12 (97,491,909 to 97,491,978, forward strand). Ensembl gene ENSG00000221479.
Gene Ontology:
Biological process: miRNA-mediated post-transcriptional gene silencing
Cellular component: RISC complex
Homologues: Orthologues: chimpanzee ptr-mir-1251 (100% identical), guinea pig MIR1251 (96% identical), mouse Mir1251 (96% identical), pig MIR1251 (96% identical), macaque MIR1251 (94% identical), rabbit MIR1251 (94% identical), dog MIR1251 (93% identical).
Diseases named in the same sentence as MIR1251 in open-access papers:
MIR1251 is named in the same sentence as 3 diseases in open-access papers, as found by Europe PMC text mining. Sharing a sentence is not in itself a finding about the gene and the disease.
MIR1251 shares sentences with these, for which no sentence is quoted: infection (1 paper); lung carcinoma (1); non-small cell lung carcinoma (1).